USP1 (ubiquitin specific peptidase 1)
Diseases named in the same sentence as USP1 in open-access papers (continued):
Sharing a sentence is not in itself a finding about the gene and the disease.
tumor (continued). "They found that USP1 mediated resistance to platinum by stabilizing Snail and then promoting tumour dissemination." (PMID 32951278, 2020). "We first assessed USP1 mRNA levels in tumor and para-tumor tissues, which revealed higher USP1 expression in tumor tissues than in para-tumor tissues." (PMID 33102219, 2020). "IHC and western blot analysis also confirmed higher levels of USP1 in HCC samples relative to those in adjacent non-tumor tissues." (PMID 33102219, 2020). "Here, we characterized the functional role of circular RNA USP1 (circ‐USP1) in the regulation of the blood‐tumour barrier (BTB) permeability and the potential mechanisms." (PMID 31654502, 2020). "Targeting USP1 with its selective inhibitor Pimozide displayed dramatic survival benefit in tumor-bearing mice." (PMID 30918246, 2019). "The level of USP1 was significantly elevated in tumor tissues and in most tumor cell lines examined." (PMID 31921663, 2019). "USP1 inhibitors have been proven effective in BRCA1 mutant tumours as USP1 is required for replication fork stability in the absence of functional BRCA1." (PMID 31769469, 2019). "In the case of USP1, a survey of the COSMIC mutation database revealed a total of 23 non-synonymous mutations in different tumor types." (PMID 23937906, 2013). "In an attempt to further clarify this issue, we used quantitative RT-PCR to analyze USP1 mRNA levels in paired normal/tumor tissue samples from four NSCLC patients." (PMID 23937906, 2013). "Aberrant overexpression is the most common finding, and it appears to be particularly frequent in cervical and gastric cancer, melanoma and sarcoma, four tumor types where USP1 results overexpressed in more than 60% of the available studies." (PMID 23937906, 2013). "In all these settings, USP1 expression was higher in tumors or tumor-derived cells than in normal samples, supporting the association of USP1 overexpression with NSCLC." (PMID 23937906, 2013). "USP1 depletion inhibits cell proliferation, migration, and tumor growth in vitro and in vivo." (PMID 39814232, 2025). "We compared USP1 expression in tumor and normal samples from the GSE149507 cohort." (PMID 39735674, 2025). "USP1 regulates DNA damage repair, cell cycle, and apoptosis, subsequently participating in tumor growth and metastasis, suggesting that USP1 may be a potential drug target." (PMID 39814232, 2025). "Based on this, it is imperative to first confirm whether the amplified effect of ML323 targeting USP1 on the tumor's innate immune response post‐RT stems from the dsDNA signaling pathway." (PMID 39976106, 2025). "Notably, USP1 depletion or a novel USP1 inhibitor I-138 dramatically delayed tumor growth in xenograft model." (PMID 39814232, 2025). "The apparently opposite roles of USP1 in regulating autophagy may be due to different cellular and molecular contexts or tumor heterogeneity." (PMID 39814232, 2025). "Alterations in USP1 activity could therefore compromise the efficacy of palbociclib by enabling tumor cells to evade CDK4/6-mediated cell cycle arrest or by improving DNA repair capacity." (PMID 40940964, 2025). "This underscores the compelling scientific rationale for targeting USP1, suggesting that pharmacological modulation of USP1 could potentially reverse the impaired activation of anti‐tumor immunity post‐RT." (PMID 39976106, 2025). "Notably, USP1 is frequently overexpressed in tumor cells and correlates with tumor progression, establishing it as a particularly attractive therapeutic target." (PMID 40136409, 2025). "Moreover, ablation of USP1 diminished the expression of ATG14 in tumor tissues, which suggested that USP1 promotes tumor growth via upregulating ATG14 expression." (PMID 39814232, 2025). "Furthermore, using a nude-mice xenograft tumor model, we noted that USP1 inhibition effectively suppressed tumor proliferation and increased the expression of NK cell-associated markers." (PMID 39735674, 2025).
tumor (continued). "However, little is known about how USP1 regulates autophagy and its mechanism in tumor progression and drug sensitivity in PDAC." (PMID 39814232, 2025). "Moreover, pharmaceutical inhibition of USP1 significantly reduces tumor formation using a novel USP1 inhibitor I-138 in PDAC xenograft model." (PMID 39814232, 2025). "The effect may be due to the oncogenic role of USP1 in tumor cells and/or tumor immune escape in tumor-infiltrating lymphocytes, the latter of which is worth further investigation." (PMID 39814232, 2025). "We observed that USP1 inhibition substantially impeded tumor growth." (PMID 39735674, 2025). "Therefore, we applied a nude-mice xenograft tumor model to further confirm the significance of USP1 inhibitors in SCLC." (PMID 39735674, 2025). "Indeed, in a CRISPR screen employing over 700 tumor cell lines including a subgroup with BRCA1/2 mutation and DNA repair defects, USP1 was found as a suitable target based on genetic dependency." (PMID 39430244, 2024). "Furthermore, we analyzed USP1 expression in 19 paired tumors and adjacent normal tissues, which showed a significant increase in USP1 expression in tumor tissues." (PMID 39513905, 2024). "In GC, USP1 has been recently reported to promote tumor metastasis by stabilizing ID2 expression." (PMID 38366146, 2024). "Tumors in mice injected with USP1−/− UMUC3 cells grew markedly slower than those in mice injected with UMUC3 cells, and the tumor volume in nude mice injected with USP1−/− UMUC3 cells was significantly smaller than that in nude mice injected with the WT UMUC3 cells." (PMID 39513905, 2024). "Moreover, the results in the xenograft mouse model indicated that shUSP1 inhibited HCC tumor growth from HLF cells, while further TAZ overexpression at least partially reversed the growth inhibition caused by USP1 depletion." (PMID 37041150, 2023). "A significant increase in CHK1 levels and activity in tumor cells caused by the silencing of BRD7 enhances tumor cell sensitivity to CHK1 inhibitors, leading to increased cell death via apoptosis, which is reversed by the simultaneous knockdown of CHK1 or USP1." (PMID 37626049, 2023). "Biologically, the increased expression of CHK1 in tumor cells caused by BRD7 silencing significantly increased cell sensitivity to CHK1 inhibitors by enhancing tumor cell apoptosis, and this effect was reversed by the simultaneous knockdown of CHK1 or USP1." (PMID 37626049, 2023). "Tumors were considered USP1-positive if USP1 was expressed in the nucleus of >55% of tumor cells." (PMID 36352191, 2023). "The USP1 protein leads to regulated DNA repair through deubiquitination and homologous recombination pathways, and inhibits cell differentiation by stabilizing tumor-promoting inhibitors of DNA-binding proteins." (PMID 37048102, 2023). "The expression levels of USP1 was higher in tumor tissues than in non-tumor tissues." (PMID 36153316, 2022). "However, reconstitution with either USP1 or MAST1 resulted in significant increase in tumor volume and weight." (PMID 35966591, 2022). "We observed that USP1 expression in CTCs was higher than in primary tumor cells." (PMID 33102219, 2020). "As we know, Cdh1 is generally accepted as a tumour suppressor, USP1 overexpression in HCC tissues may partially due to the dysregulation of Cdh1." (PMID 32951278, 2020). "Interestingly, the only clinical characteristics positively correlated with USP1 levels were serum α-fetoprotein level (P = 0.013) and tumor number (P = 0.028)." (PMID 33102219, 2020). "The role of USP1 in processes that are frequently deregulated in tumor cells, suggests that this enzyme may represent a particularly promising target for anticancer therapy." (PMID 22701671, 2012). "Consequently, USP1 is considered a promising synthetic lethal target in HRD‐mutant tumours and may act synergistically with PARPis." (PMID 41537447, 2026).
tumor (continued). "Taken together, these findings indicate that USP1 inhibitor markedly enhances the innate immune response within tumor tissues following RT and suggest that targeting USP1 may substantially influence the immunophenotypic remodeling of the tumor microenvironment post‐RT." (PMID 39976106, 2025). "Thus, the tumor tissue showed a positive correlation between USP1 and survivin protein levels." (PMID 36153316, 2022). "In addition, USP1 inhibition can significantly inhibit the metastasis of tumor cells." (PMID 36357365, 2022). "Targeting USP1 activity may thus be an alternative therapeutic strategy in MYC-driven tumours." (PMID 36240066, 2022). "Moreover, USP1 stabilizes inhibitors of DNA binding proteins, which are overexpressed in tumours." (PMID 32951278, 2020). "An example is that USP1 and USP18 promote M2 polarization and tumour progression by deubiquitinating and stabilizing attractive receptors, including CXCR4 and CSF1R respectively in tumour-associated macrophage." (PMID 41562074, 2025). "USP1 deubiquitinates and stabilizes ATG14, thus remarkably promoting malignant features, such as cell proliferation, migration, autophagy, and tumor growth in PDAC." (PMID 39814232, 2025). "The development of a first in class USP1 inhibitor, i.e., KSQ-4279, capable to inhibit tumor growth in models partially sensitive to PARP inhibitors and to induce durable tumor regression in combination with PARP inhibitors is ongoing." (PMID 39430244, 2024). "Several deubiquitination enzymes, such as CSN5, USP1, USP19, and STAMBPL1, prevent the ubiquitin degradation process of survivin and stabilize its expression, leading to tumor progression and therapeutic resistance 48-50." (PMID 38356707, 2024). "Expression of USP1 was markedly increased in GBM and, to a lesser extent, in AS compared to the non-tumor group." (PMID 37892185, 2023). "We therefore evaluated the effectiveness of the USP1/UAF inhibitor, ML323 in vivo, and analysed its effect on the growth of transplanted WT Eμ-Myc tumours." (PMID 36240066, 2022). "Altogether, our results showed that, upon cisplatin treatment, USP1-depletion downregulates MAST1 level and induces apoptosis that hampers tumor progression." (PMID 35966591, 2022). "Furthermore, in the in vivo experiments in mice, using tail vein injection of sh-USP1, the growth of tumors in mice was apparently inhibited, thereby resulting in a significantly prolonged survival period, which is of reference value for clinical researches on tumor therapies." (PMID 35053496, 2022). "In this study, pharmacological inhibition of USP1 and MAST1 using pimozide and lestaurtinib synergistically boosted the effect of cisplatin toxicity on tumor growth." (PMID 35966591, 2022). "The combined targeting of USP1 and MAST1 by pimozide and lestaurtinib synergistically enhanced cisplatin sensitivity in the mouse xenografts, significantly reducing tumor volume and weight compared with a single treatment of pimozide or lestaurtinib." (PMID 35966591, 2022). "The overexpression and positive correlation of USP1 and RPS16 are also observed in tumor tissues of HCC patients." (PMID 34154657, 2021). "UAF1/USP1, UAF1/USP12, and UAF1/USP46 complexes play vital roles in DNA repair processes and tumor pathogenesis." (PMID 33247121, 2020). "USP1 and its cofactor WDR48 are involved in the tumour progression of HCC by deubiquitinating and stabilizing their substrates." (PMID 32951278, 2020). "USP1 is a member of the USP family, which can deubiquitinate a wide range of substrates; furthermore, USP1 and UAF1 form a deubiquitinating enzyme complex that is involved in a variety of biological processes, including DNA repair and tumor pathogenesis." (PMID 40369332, 2025). "USP1 short hairpin RNA (shRNA) can rapidly degrade ID1, induce p21-mediated cell-cycle arrest, and initiate an osteogenic differentiation program in osteosarcoma, providing a target for tumor differentiation therapy." (PMID 41146039, 2025).
tumor (continued). "As a USP1 inhibitor, ML323 reduces macrophage infiltration, regulates CD4+ T cell differentiation, and inhibits Th17 cell development, maintaining immune balance and exerting anti-tumor effects." (PMID 39868366, 2024). "Furthermore, USP1 and survivin protein expression showed a positive correlation, whereas miR-216a-5p and DR5 were inversely correlated in RCC tumor tissues." (PMID 36153316, 2022). "The correlation coefficients between USP1 expression and the abundances of six immune infiltrates (B cells, CD8 + T cells, CD4 + T cells, macrophages, neutrophils and dendritic cells) were analysed using Spearman tests (tumour purity adjusted)." (PMID 32951278, 2020). "Interestingly, depletion of USP1 remarkably decreased tumor weight and tumor volume, which did not affect the body weight." (PMID 39814232, 2025). "Furthermore, analyses of clinical specimens of colorectal cancer indicate that the expression levels of USP1 in nontumor cells within the tumor pre‐RT correlate with the degree of immune activation and therapeutic efficacy post‐RT." (PMID 39976106, 2025). "Co-treatment with USP1 and MAST1 inhibitors abrogated tumor growth and synergistically enhanced cisplatin efficacy, suggesting a novel alternative combinatorial therapeutic strategy that could further improve MAST1-based therapy in patients with cisplatin-resistant tumors." (PMID 35966591, 2022). "Furthermore, the immunohistochemical analysis of the xenograft tumor tissues showed significantly reduced USP1 and MAST1 expression in the USP1KO tumors compared with the mock xenograft, and that expression was regained by reconstitution with USP1 or MAST1." (PMID 35966591, 2022). "On the other hand, our findings provide the basis for a relocation assay that can be easily implemented in a high throughput setting to search for drugs that may dissociate the USP1/UAF1 complex and thus interfere with the activity of this complex in tumor cells." (PMID 22701671, 2012). "In tumor tissues from 77 LARC patients at The First Affiliated Hospital, Sun Yat‐sen University, a distinct inverse correlation was observed between USP1 expression in nontumor cells before RT and the infiltration of cytotoxic CD8+ T lymphocytes after treatment." (PMID 39976106, 2025).
infection (5 papers, 2017 to 2026). The state of being infected such as from the introduction of a foreign agent such as serum, vaccine, antigenic substance or organism. "Relative to DMSO, C527 treatment diminished pSTAT1 levels in cells infected with WT virus but had little effect on ΔUL138STOP infection, suggesting a role for USP1 in the UL138-associated induction of pSTAT1." (PMID 37289831, 2023). "This was observed from early (24 h post infection, hpi) to late (72 hpi) times in infection, supporting a role for USP1 on vDNA." (PMID 41533576, 2026). "Only 25% of the novel junctions arising from depletion of USP1–PCNA/FANCD2/FANCI overlap with ∆UL138STOP infections, suggesting an important role for UL138 in directing these pathways." (PMID 41533576, 2026). "Further, depletion of USP1–PCNA/FANCD2/FANCI was sufficient to compromise viral genome integrity in WT infection." (PMID 41533576, 2026). "The combined depletion of USP1–PCNA/FANCD2/FANCI in WT infection triggered a robust increase in inversions and deletions across the entire CMV genome (lightest blue bars) relative to the siNTC." (PMID 41533576, 2026). "In support of this, we observed that USP1 co-localized with UL138 in the Golgi apparatus during infection." (PMID 41533576, 2026). "By contrast, the rearrangements in the UL region arising in UL138-mutant infection occurred independently of repeat sequences and USP1–PCNA/FANCD2/FANCI." (PMID 41533576, 2026). "The cytoplasmic localization of USP1 is also observed in uninfected cells and infected cells early infection and has been previously documented by others." (PMID 41533576, 2026). "At late stages of infection (72 hpi), USP1 was observed in juxtanuclear structures resembling viral assembly compartments." (PMID 41533576, 2026). "We further examined the changes in USP1 mRNA and protein levels after infection with different influenza viruses (MOI = 0.01) in MDCK, A549, and HEK-293 cells using RT-qPCR and Wb techniques, respectively." (PMID 40369332, 2025). "To elucidate the molecular mechanism underlying USP1-mediated regulation of influenza virus replication in MDCK cells, we identified the USP1 interacting partners during infection with the H1 N1 virus." (PMID 40369332, 2025). "While we show that pSTAT1 depends on UL138 and USP1 at late times during infection in fibroblasts, we were surprised that neither total or phosphorylated levels of TBK1 were affected by UL138 or USP1 as a possible mechanism to sustain pSTAT1." (PMID 37289831, 2023). "Another S-Plot-significant protein found to be downregulated in blood stream infection patients in our dataset was Ubiquitin carboxyl-terminal hydrolase 1 (USP-1)." (PMID 28235076, 2017). "At 48 hours post infection (hpi), UL138myc IP co-precipitated USP1." (PMID 37289831, 2023). "To gain more insight into the role of UL138 and USP1–PCNA/FANCD2/FANCI in controlling DDR pathways and maintaining CMV genome integrity, we analyzed the distribution and type (e.g. inversions, deletions, or duplications) of structural variants in each of our infection and knockdown conditions." (PMID 41533576, 2026). "PCNA and FANCD2 were also relocalized to RCs in ∆UL138STOP infection, which suggests this phenomenon occurs independently of UL138, as was observed for USP1." (PMID 41533576, 2026). "Compared to NTC, depletion of PCNA/FANCD2/FANCI or PCNA/FANCD2/FANCI combined with USP1 increased viral genome synthesis in WT and ∆UL138STOP infections." (PMID 41533576, 2026). "By contrast, in ∆UL138STOP infection, SNV counts increased in the USP1–PCNA/FANCD2/FANCI knockdown relative to any other knockdown in ∆UL138STOP infection." (PMID 41533576, 2026).
infection (continued). "After the onset of viral DNA synthesis, pSTAT1 levels are elevated in infection and this depends upon UL138 and USP1." (PMID 37289831, 2023). "This localization was not dependent on UL138, as USP1 was also localized to RCs in ∆UL138STOP infection." (PMID 41533576, 2026). "USP1 depletion in ∆UL138STOP infection increased mUb–PCNA, but did not have a statistically significant effect on mUb–FANCD2 compared to the NTC control." (PMID 41533576, 2026). "Compared to the NTC, USP1 depletion in WT infection led to a modest, but significant, increase in mUb–PCNA and mUb–FANCD2 at 48 hpi and 72 hpi, respectively, resembling the phenotype observed in ∆UL138STOP infection." (PMID 41533576, 2026). "USP1 constrains CMV genome synthesis and overall replication during productive infection of fibroblasts, paralleling the observation that chemical inhibition of USP1 stimulates virus replication in hematopoietic progenitor cells where viral latency is established." (PMID 41533576, 2026). "At the protein level, the expression of USP1 protein levels was significantly upregulated in all four influenza viruses infected with USP1 in A549 cells and MDCK cells, whereas the expression of USP1 protein levels was upregulated in HEK293 cells only with BY infection." (PMID 40369332, 2025). "Finally, we were intrigued by finding that depletion of USP1–PCNA/FANCD2/FANCI did not increase junctions beyond the disruption of UL138 in infection." (PMID 41533576, 2026). "Of note, USP1 knockdown increased vDNA synthesis and virus yield in ∆UL138STOP infection, but the increase in yield was not statistically significant." (PMID 41533576, 2026).
kidney disease (2 papers, 2021 to 2022). "Although recent reports indicate that circ‐USP1 is involved in the dysregulation of endothelial cell functions, its role in kidney diseases remains largely unclear." (PMID 33484504, 2021).